MS4A8 (membrane spanning 4-domains A8)
Description:
May be involved in signal transduction as a component of a multimeric receptor complex.
Synonyms: 4SPAN4; MS4A8B; MS4A4; CD20L5
Tractability: Antibody: its Gene Ontology location is reachable by antibodies, with high confidence; UniProt predicts a signal peptide or a membrane-spanning region.
Gene: Protein-coding gene on chromosome 11 (60,699,585 to 60,715,811, forward strand). Ensembl gene ENSG00000166959.
Subcellular location: Membrane
Gene Ontology:
Biological process: cell surface receptor signaling pathway
Cellular component: plasma membrane; membrane
Genetic constraint (gnomAD): Loss-of-function variants: 23 observed, 22.52 expected, observed/expected ratio (o/e) 1.02, 90% interval 0.73 to 1.45. The upper end of that interval is the gene's LOEUF score, 1.45, which puts it in group 5 of 6, group 1 being the genes least tolerant of losing a copy. Missense variants: 299 observed, 324.15 expected, observed/expected ratio (o/e) 0.92, 90% interval 0.84 to 1.01. Synonymous variants: 137 observed, 132.31 expected, observed/expected ratio (o/e) 1.04, 90% interval 0.9 to 1.19.
Homologues: Orthologues: chimpanzee MS4A8 (99% identical), macaque MS4A8 (88% identical), rat Ms4a8 (65% identical), mouse Ms4a8a (62% identical), rabbit MS4A8 (60% identical), pig MS4A8 (54% identical). Paralogues in human: MS4A12 (36% identical), MS4A15 (34% identical), MS4A18 (34% identical), MS4A1 (24% identical), MS4A4A (24% identical), MS4A10 (22% identical), MS4A6A (20% identical), MS4A7 (20% identical), MS4A2 (20% identical), MS4A3 (19% identical), MS4A4E (19% identical), MS4A14 (18% identical), and 4 more.
Diseases named in the same sentence as MS4A8 in open-access papers:
MS4A8 is named in the same sentence as 7 diseases in open-access papers, as found by Europe PMC text mining. Sharing a sentence is not in itself a finding about the gene and the disease. The quoted sentences say what the papers report.
tumor (3 papers, 2022 to 2025). "CD24, CLDN3, WFDC2, and TACSTD2 genes were present in all the tumour clusters of all samples, and the genes C1orf194, C20orf85, MS4A8, ODF3B, RSPH1, and TPPP3 appear to be co‐expressed." (PMID 41160707, 2025). "Protein levels of MS4A10, MS4A8, MS4A7, PCNA, BAX, Bcl-2, Caspase-3, and cleaved Caspase-3 were measured in tumor tissues." (PMID 36438804, 2022).
MS4A8 also shares sentences with these, for which no sentence is quoted: bacterial infections (1 paper); cancer (1); colorectal cancer (1); glioma (1); mammary tumors (1); prostate carcinoma (1).